TERT (telomerase reverse transcriptase)
Diseases named in the same sentence as TERT in open-access papers (continued):
Sharing a sentence is not in itself a finding about the gene and the disease.
tumor (continued). "There are also indications that the presence of specific mutations like the TERT promoter mutations may influence imaging characteristics such as tumor location, cortical extension, and peritumoral tissue response." (PMID 41007844, 2025). "TERT protein expression was linked to greater tumour thickness and decreased survival." (PMID 40361989, 2025). "In this case, the tumor was completely resected; however, recurrence occurred within two years, likely due to adverse prognostic factors such as advanced age and the presence of a TERT promoter mutation." (PMID 41013491, 2025). "Stage-specific analysis further identified key drivers of distinct disease transitions including EZH2 and PLK1 as major regulators of androgen dependence in mHSPC, and TERT as a hallmark of mCRPC, highlighting its role in telomere maintenance and tumor progression." (PMID 41402347, 2025). "The identified TERT promoter mutation in this case suggests that specific molecular alterations may contribute to the tumor’s invasive and metastatic potential." (PMID 41488090, 2025). "Notably, HBCV-HCCs with the same driver mutation, HBV integration at the TERT promoter, tended to develop later and showed a better prognosis post-tumor resection than HBV-HCCs." (PMID 39743539, 2025). "TERT’s association with cell proliferation could play an important role in tumour growth and progression." (PMID 40307280, 2025). "Moreover, large‐scale genomic surveys identified mutations in the telomerase reverse transcriptase (TERT) gene, which encodes the catalytic reverse transcriptase subunit of telomerase, as one of the most prevalent genetic changes in a wide variety of tumours." (PMID 40214124, 2025). "The convergence of these two alterations may provide a selective advantage in certain HCC subtypes, as TERT mutations sustain chromosomal stability and cell immortality, while β-catenin activation enhances tumor initiation and progression." (PMID 40243493, 2025). "Previously, we quantified FUS‐DDIT3 and the TERT promoter mutation C228T using real‐time PCR and droplet digital PCR (ddPCR) and showed a correlation between ctDNA concentrations, the clinical course, and tumor burden." (PMID 39980272, 2025). "It is important to note that TERT promoter mutations tend to be subclonal in differentiated carcinomas, meaning they are present in only a portion of tumor cells, while they are clonal in poorly differentiated thyroid carcinoma (PDTC) and ATC, indicating they are present in all or most tumor cells." (PMID 39744583, 2025). "In particular, the TERT-124 [C > T] promoter mutation may be linked to heightened aggressiveness, contributing to the tumor's more invasive characteristics." (PMID 39871386, 2025). "TERT is an important cancer hallmark, primarily known for maintaining telomere length by preventing cellular senescence and ensuring immortality, but it also has telomere-independent roles responsible for tumor progression." (PMID 39858033, 2025). "TERT promoter mutations have been associated with increased cortical extension and necrosis, as well as specific tumor locations (more common than their wild-type counterparts in the insula and hemispheric lobes but rarer in the basal nuclei, thalamus, brainstem, and cerebellum)." (PMID 41007844, 2025). "This may be attributed, at least in part, to the discovery of a 17 mm tumor with a subclonal TERT promoter mutation, which, to our knowledge, represents one of the smallest miFTC/miOTC with a TERT promoter mutation to date." (PMID 39363120, 2024). "The irregular margin is presumed as attraction of surrounding tissue by peripheral stromal traction, which may be relevant to the association between TERT promoter mutation and tumor aggressiveness." (PMID 38961252, 2024).
tumor (continued). "This could stem from the bidirectional effects of TERT mutations, where the neuroprotection and tumor growth effects counteract each other." (PMID 38315329, 2024). "In tumor cells, the TERT promoter is reported to be frequently methylated, but there has been some debate about whether TERT mutations and promoter methylation are mutually exclusive, and this has been explored in cell lines." (PMID 39406235, 2024). "Our allele-specific data show that TERT promoter mutation and promoter methylation may indeed co-occur in a single patient tumor, but that these two alterations may be on different alleles." (PMID 39406235, 2024). "The gene encoding promyelocytic leukemia (PML), a tumor suppressor primarily expressed in the nucleoplasm, interacts directly or indirectly with TERT in HepG2, U2OS, and HFF cell lines, negatively regulating telomerase activity and eventually resulting in telomere shortening." (PMID 38278800, 2024). "It is also noteworthy to highlight that the reporting of TERT promoter mutations may be significantly influenced by intratumoral heterogeneity especially when examining differences between localized tumor and metastatic specimens." (PMID 37462445, 2024). "TERT amplification is associated with tumor metastasis and poor prognosis." (PMID 38970069, 2024). "TERT promoter mutations are associated with poor prognosis and may promote tumour progression and metastasis." (PMID 38966061, 2024). "In clinical practice, TERT mutation detection not only provides essential information for treating recurrent RGNT cases but also may help assess tumor aggressiveness and long-term survival." (PMID 39457636, 2024). "One tumor was found to have a TERT promoter mutation as well as a homozygous deletion of CDKN2A/B." (PMID 38720399, 2024). "High-risk neuroblastoma tumours frequently suffer from TERT rearrangement and ATRX inactivation." (PMID 39715281, 2024). "Importantly, TERT promoter mutations are associated with worse clinical outcomes in most BC studies, further highlighting the role of telomerase activation in tumor progression and recurrence." (PMID 38612507, 2024). "While the presence of high frequencies of TERT promoter mutations in metastatic PTCs was already demonstrated to be associated with tumor aggressiveness, the enrichment of ATM pathogenic mutations in the LNMs of PTC patients with 4 or more DMs observed in this study is noteworthy." (PMID 39030377, 2024). "An indeterminate tumor is considered malignant if NGS results reveal BRAF or TERT mutations." (PMID 39235852, 2024). "Similarly, SFTs with TERT promoter mutations were significantly associated with clinical features of malignancy, such as older age, larger tumor size, higher mitotic activity, necrosis, and higher grade." (PMID 38239634, 2023). "Therefore, TERT mRNA expression should be higher in tumor tissues when the TERT promoter and BRAF mutations coexist." (PMID 37296851, 2023). "In the cases with TERT mutation, neutrophils showed significantly higher expression of cytokines, resulting in significant homing of more neutrophils to the tumor and further tumor progression." (PMID 38275375, 2023). "Interestingly in patient A, we were unable to detect the TERT promoter mutation in the progressed tumour, and of note this was resected after radiotherapy." (PMID 36882706, 2023). "This supports the theory that a TERT promoter mutation may be the initial genetic event in carcinogenesis that promotes tumor cells to acquire other aggressive mutations." (PMID 36672362, 2023).
tumor (continued). "Considering this trend, our results may support the importance of somatic mutations in NMIBC recurrence and the fact that somatic mutations in EGFR and TERT have a prognostic value for tumour recurrence in NMIBC." (PMID 37892022, 2023). "This last combination assumes a particular interest since inhibition of TERT could change the tumor-associated microenvironment toward an immune-active one." (PMID 38201248, 2023). "It should be noted that assessment of activated vs. exhausted T cells could help to confirm anti-tumor immunity in both TERT-deficient and 6-thio-dG treated mice." (PMID 37085672, 2023). "The concordance with the TERT mutation status between CSF and tumor tissue yielded 83.3%." (PMID 37822669, 2023). "In a study of 95 HCC patients, researchers analyzed the distribution of common HBV DNA integration sites using targeted sequencing and found frequent HBV integration in TERT, along with increased TERT mRNA expression, which was associated with more aggressive tumor behavior." (PMID 36672482, 2023). "Another mutation in the telomerase reverse transcriptase (TERT) promotor is also associated with tumor recurrence and decreased survival rates, although there is controversy over whether or not the TERT mutation is associated with increased CNM." (PMID 37623013, 2023). "Mutations in the TERT promoter region increase gene expression and activate telomerase activity, thus giving tumor cells an infinite potential to proliferate and encouraging tumor development and spread." (PMID 37830090, 2023). "Moreover, whole genome sequencing of 326 cell lines derived from different cancer types showed that 60 lineages harboured mutated TERT promoters with a mutation rate similar to that of the respective primary tumours." (PMID 38033865, 2023). "Moreover, both TERT deficiency and dysfunctional telomeres decreased lung tumor implantation and expression of the tumor progression markers Mmp9, Egfr, Hmox1 and c-MET." (PMID 37085672, 2023). "Additionally, MIBC patients harboring the TERT c.1-124C>T mutation at both follow-up time points had the highest risk of tumor progression compared with the other MIBC patients (HR 6.405, p = 0.002)." (PMID 38068899, 2023). "Telomerase reverse transcriptase (TERT), a gene encoding a crucial subunit of the telomerase enzyme, plays a significant role in establishing cancer cell immortality and is under suspicion for its potential contribution to tumor progression." (PMID 37848472, 2023). "In addition, this SNP is associated with the prognostic value of TERT somatic mutations across a variety of tumor types; however, larger sample sizes would be necessary to evaluate such association in PTC." (PMID 37569841, 2023). "TERT mutation appears to be associated with more aggressive forms of the tumor." (PMID 37629774, 2023). "In patient B the TERT promoter variant was detected in all tumours." (PMID 36882706, 2023). "HBV integration at the TERT promoter is associated with more aggressive tumor behavior." (PMID 37108816, 2023). "In a multivariate logistic regression model that included BRAFV600E mutation, TERT promoter mutations, age at diagnosis, tumor size, ATA stage and TNM stage, TERT promoter mutations remain a significant predictor of persistent disease (P 0.01, odds ratio 2.7, 95% CI 1.2-5.9)." (PMID 37859987, 2023). "We determined whether the association between B cell infiltrate and TERT expression (Bhigh/TERThigh phenotype) was specific or was shared by other conserved tumor antigens previously documented in HNSCC tumors." (PMID 36909826, 2023). "A TERT promoter mutation may have important prognostic implications as a strong predictor of tumor relapse, being associated with the development of distant metastases in PTCs." (PMID 37046812, 2023). "In addition, entropy values were also significantly higher in TERT mutations, indicating increased heterogeneity within the tumor environment." (PMID 38054695, 2023).
tumor (continued). "Furthermore, tumours exhibiting BRAF V600E or TERT promoter mutations are less likely to spawn iodine avid metastases and are associated with poorer patient outcomes." (PMID 37352166, 2023). "Since aberrant TERT expression is associated with tumor development, L1 insertion near the TERT locus may play a role in carcinogenesis." (PMID 38136578, 2023). "However, TERT promoter region mutations were associated with malignant histology, necrosis, large tumor size, and older age." (PMID 37980418, 2023). "We found that EGFR mutations or TERT mutations might have prognostic value for the tumour recurrence of NMIBC." (PMID 37892022, 2023). "Furthermore, TERT promoter mutations are an early genetic event in gliomagenesis, explaining the observed homogeneous distribution among cellular tumor subclones." (PMID 38201248, 2023). "Multivariate Cox regression analyses could verify the TERT amplification status in patients with a pT1N0-3 tumor stage as an independent risk factor for poor survival (HR = 2.440, 95% CI 1.095–5.440, p = 0.029)." (PMID 37848472, 2023). "Distribution of TERT promoter mutations in tumour types and histologic subtypes." (PMID 38033865, 2023). "Through our cascaded deep learning approach, we learned that TERT promoter mutation status is associated with tumor cell size enlargement and nuclear atypia with prominent nuclear atypia, which is often associated with aggressive tumor behavior." (PMID 36984536, 2023). "The tumor mutation burden was found to be high in 25 cases with the TERT promoter mutations." (PMID 35135543, 2022). "As TERT mutations have been observed to affect tumor cell sensitivity to DNA damage (i.e., from radiation or chemotherapy), we hypothesized whether there may be an interaction between TERT mutations and radiation dose response." (PMID 36380219, 2022). "Compared to the initial grossly resected tumor specimen, the recurrent tumor possessed loss of heterozygosity of 1p, 10q, 17q, and 19q chromosomes, as well as a new C228T TERT promoter mutation, while the status of wild-type IDH1/IDH2 and mutant BRAF V600E was unchanged." (PMID 36703629, 2022). "As many PTC tumours lack TERT expression or promoter mutations, it will be interesting to evaluate whether TERC can serve as a prognostic factor in those PTC patients." (PMID 36394204, 2022). "Consequently, tumor tissue from initial biopsy or surgery was most often tested for TERT promotor mutation at time of recurrence or even retrospectively for the purpose of the present study (9/10 patients with wait-and-scan approach, 90%)." (PMID 34902093, 2022). "Therefore, by inhibiting the expression of transcription factors, it is hoped that the tumor burden of patients with TERT promoter mutations can be reduced and the survival time will be prolonged." (PMID 35903534, 2022). "Notably, co‐occurrence of TERT promoter mutation and methylation was exclusively observed in clinically aggressive tumours and were more frequent in advanced histology tumours." (PMID 35979662, 2022). "Besides, TERT mutations positively correlated with a higher tumor mutational burden (TMB) value, neoantigen load, and tumor purity." (PMID 35903534, 2022). "Unexpectedly, TERT promoter mutations were related with smaller tumor sizes in our study." (PMID 35311090, 2022). "Mutations in the TERT promoter represent the genetic underpinnings of tumor cell immortality." (PMID 36114166, 2022). "However, TERT mutations in ctDNA samples were correlated with large intrahepatic tumor size and increased mortality." (PMID 35311090, 2022). "TERT, in which mutations were detected in all six cases, encodes telomerase reverse transcriptase, which is a major factor in telomerase reactivation and accelerates tumor progression." (PMID 34904383, 2022).
tumor (continued). "The frequency of TERT promoter mutation in NMIBC was higher in normal urothelium than that in tumor in current study, these data could possibly indicate that tumorigenesis of NMIBC was associated with TERT promoter mutation." (PMID 36198773, 2022). "Furthermore, the high incidence of TERT mutations and TERT promoter methylation in high grade IDH2 tumours, suggests that these events, through activation of telomerase, have prevented the senescent phenotype and bring about high-grade IDH2 tumours." (PMID 36042521, 2022). "Despite rGBM frequently hosting TERT promoter mutations supporting tumor cells’ immortalization, the pharmacological inhibition of TERT abnormal transcription has not yet been considered for extensive investigation, let alone sparse preclinical studies on GBM models." (PMID 36009473, 2022). "In addition, mutations in the TERT promoter reactivate telomerase, which prevents telomere shortening and leads to the immortalization of tumor cells." (PMID 35806478, 2022). "ETV6-NTRK3 gene fusion involving multiple sites may drive tumorigenesis, while mutations in the TERT promoter region may be a factor driving tumor progression." (PMID 36585729, 2022). "In a recent study, we observed that the TERT rs2736100 mutation (either TG or GG) was significantly associated with some high-risk clinicopathological features such as tumor spread, extrathyroidal extension, central/lateral lymph node metastases, and Stage T III and IV disease." (PMID 36704521, 2022). "In our recent study, we observed that the TERT rs2736100 mutation (either TG or GG) was significantly associated with some high-risk clinicopathological features such as tumor spread, extrathyroidal extension, central/lateral lymph node metastases, and Stage T III and IV disease." (PMID 36704521, 2022). "Additionally, including molecular factors that are associated with tumor recurrence/progression would be of interest, such as the TERT promoter mutation." (PMID 34601710, 2022). "Previous studies revealed the inconsistent relationship between TERT mutations and tumor sizes." (PMID 35311090, 2022). "However, most of the current studies on TERT promoter mutations focus on human tumor diseases, and there are few studies on chicken-related tumor diseases." (PMID 35739589, 2022). "Significantly elevated expression levels of human TERT (hTERT) have been found in most human malignancies, such as sarcomas, brain tumors, colorectal tumors, and breast cancer, increasing the risk of tumor recurrence." (PMID 35739589, 2022). "Here, we demonstrate gene expression mediated by DNA amplicons both in vitro and in vivo and show the immunogenicity of a DNA amplicon encoding for a tumor associated antigen (i.e. Telomerase Reverse Transcriptase—TERT) in wild-type mice as compared to plasmid DNA-EP." (PMID 35668533, 2022). "Histological examination and subsequent immunohistochemical analysis of LCA CD45 revealed that four out of the five available tumour specimens showed lymphocyte infiltration, which has been recently associated with tumour cell‐unspecific positivity for TERT expression." (PMID 35979662, 2022). "Studies have shown that although telomerase expression is increased in tumor cells with TERT promoter mutations, the observed telomeres are still very short, suggesting that the key effect of TERT promoter may occur after telomeres become extremely short." (PMID 35903534, 2022). "Given the significant associations between elevated EGFR mRNA and protein phosphorylation levels, TERTp mutation and TERT expression in tumor tissue from patients with GBM, we tested for a potentially causal relationship using three independent experimental approaches." (PMID 36130485, 2022). "Thus, tumour status for TERT promoter mutations, a highly cancer‐specific TERT expression‐related alteration, has been widely used to predict disease outcome in certain cancers." (PMID 35979662, 2022).